CLDN5 (claudin 5)
Diseases named in the same sentence as CLDN5 in open-access papers (continued):
Sharing a sentence is not in itself a finding about the gene and the disease.
depression (continued). "Moreover, chronic down-regulation of Cldn5 expression with an adeno-associated virus including a short hairpin RNA specific to Cldn5 was sufficient to induce social avoidance and depression-like behaviors as assessed by decreased sucrose preference and increased immobility in the forced swim test." (PMID 30102966, 2018). "Additional research is needed to test the replicability of these associations, determine their overlap with other stress-related psychiatric conditions like depression, and evaluate temporal associations between PTSD, CLDN5 DNAm, and neuropathology biomarkers." (PMID 41358302, 2025). "Preclinical studies have implicated claudin-5 (CLDN5), a protein integral to the integrity of the BBB tight junctions, in the pathogenesis of depression." (PMID 41358302, 2025). "Elevated serum Cldn5 levels are reported in schizophrenia, bipolar disorder, depression, and OCD, whereas increased occludin is noted in ADHD and autism, suggesting shared BBB dysfunction across psychiatric conditions." (PMID 40940757, 2025). "Specifically, the downregulation of the TJ protein claudin-5 in the prefrontal cortex promotes anxiety-like and depression-like behaviors, including social avoidance, in females." (PMID 40725164, 2025). "On the other hand, peripheral levels of claudin-5 were increased in a small sample (n = 40) of patients with depression compared to healthy controls; in these patients, levels of claudin-5 and TNF-α were positively correlated." (PMID 39157756, 2024). "A study of biobank samples found that functional polymorphisms of the CLDN5 and IL6 genes had an interactive effect on vulnerability to depression following exposure to stress." (PMID 39157756, 2024). "Depression with high levels of TNF-α stimulates NF-κB, then elevates histone deacetylase 1 activity and represses claudin-5 expression, resulting in loss of tight-junction proteins and disruption of blood-brain barrier." (PMID 38459460, 2024). "Reduced CLDN5 expression has been reported in patients with psychiatric disorders, including major depression and schizophrenia." (PMID 38928202, 2024). "Downregulation of CLDN-5 in the prefrontal cortex promoted anxiety-like and depression-like behaviors in mice." (PMID 38338697, 2024). "Preliminary results in humans also suggest that claudin-5 is involved in the pathogenesis of depression." (PMID 39157756, 2024). "Claudin-5 is the most enriched tight junction protein in the BBB and its dysfunction is implicated in depression." (PMID 38033588, 2023). "Reduced CLDN5 expression was also observed in post-mortem tissue of unmedicated individuals with major depressive disorder compared to healthy controls." (PMID 37937070, 2023). "In two small human studies from the same group, claudin 5 gene expression was downregulated in the nucleus accumbens in patients with depression." (PMID 37700368, 2023). "In a mouse model of depression, claudin 5 (a tight cell junction protein) was decreased in the nucleus accumbens." (PMID 37700368, 2023). "To confirm that loss of Cldn5 in the female PFC plays a causal role in the establishment of anxiety- and depression-like behaviours we used an adeno-associated virus (AAV)-mediated approach to conduct functional studies." (PMID 35013188, 2022). "Claudin-5 as a direct oestrogen target is one of the proteins which mediates sex differences in neurological disorders such as depression and anxiety." (PMID 36362131, 2022). "Chronic social stress, according to a study using a mouse model of depression, has been shown to decrease the expression of claudin-5 in mice." (PMID 35634314, 2022). "Using immunohistochemistry and qRT-PCR, we show that the expression of claudin-5 is reduced in the hippocampus of individuals diagnosed with major depression or schizophrenia." (PMID 33139732, 2020). "We observed significantly reduced claudin-5 levels in the depression (*P = 0.0158) and schizophrenia (**P = 0.0073) patient groups in the hippocampus grey matter." (PMID 33139732, 2020).
depression (continued). "We found reduced expression of claudin-5 in the hippocampus of patients diagnosed with depression and schizophrenia." (PMID 33139732, 2020). "Epigenetic modifications are also present at the CLDN5 promoter in human depression, with lower repressive methylation in subjects with MDD treated by antidepressant medication at time of death." (PMID 31974313, 2020). "Claudin-5 has emerged as a potential mediator of these effects with several studies identifying downregulation of claudin-5 in numerous models of depression." (PMID 30691500, 2019). "Similarly, postmortem studies suggest that CLDN5 protein is reduced in the hippocampi of men and women with depression and schizophrenia, with greater reductions in CLDN5 expression as a function of more years of chronic psychiatric symptoms." (PMID 41358302, 2025). "Postmortem human studies also suggest that CLDN5 expression is substantially reduced in the nucleus accumbens from untreated depressed men and women, and in the ventromedial prefrontal cortex (vmPFC) of women with depression." (PMID 41358302, 2025). "Compared to OCLN and ZO-1, CLDN-5 and VE-cad are proved to be more vulnerable to H2O2, whose OS-causing depression could be erased by FGFC1 at high concentration (100 μM)." (PMID 39195457, 2024). "Disruption or reduction of claudin-5 may be involved in the pathophysiology of various diseases, including schizophrenia, depression, and Alzheimer’s disease." (PMID 39768195, 2024). "In this study, the administration of prednisolone caused decreased locomotor activity and anxiety-like and depression-like behavior; intriguingly, this occurred without changes in the expression of claudin-5 and -12." (PMID 38203447, 2023). "We showed that CLDN5 expression is reduced in the NAc of depressed patients in line with clinical studies reporting altered cerebrospinal fluid to serum ratio of peripheral markers in depression indicative of greater BBB permeability." (PMID 31974313, 2020). "In mice, Cldn5 ablation enhanced BBB permeability and allowed infiltration of large proteins up to ∼69 kDa (e.g., IL-6) into mouse brain parenchyma and was associated with depressive-like behavior and behavioral impairments characteristic of schizophrenia and depression." (PMID 36549907, 2023). "Additionally, disruption of claudin-5 expression has been implicated in numerous disorders including schizophrenia, depression and traumatic brain injury, yet its role in epilepsy has not been fully deciphered." (PMID 35422069, 2022). "Furthermore, dysfunction of the BBB, in particular the tight junction protein claudin-5, in depression, has been shown to exacerbate behavioural dysfunction in the mouse chronic social defeat stress model of depression and contribute to immune cell infiltration." (PMID 33139732, 2020). "Cldn5 knockdown in the medial prefrontal cortex (PFC) induced anxiety- and depression-like behaviors." (PMID 36978081, 2023). "It was validated and determined that CLDN5 and TBC1D1 were the hubs of genetic links between ED and depression." (PMID 38111702, 2023). "After identification and validation, CLDN5 and TBC1D1 were regarded as the hub genetic links of ED and depression." (PMID 38111702, 2023). "We measured three tight cell junction proteins (JAM-A, claudin 5 and occludin), and additionally the ICAM-1/collagen IV ratio in the later-life depression and later-life control groups." (PMID 37700368, 2023). "Claudin-5 downregulation would increase BBB permeability in neurodegenerative disorders, such as Alzheimer’s disease and depression." (PMID 34068233, 2021). "Analysis of tight junction transcripts revealed discordant results with significant increases in CLDN5, OCLN and mRNA in bipolar and depression brains samples." (PMID 33139732, 2020).
depression (continued). "Cldn5 knockdown in the nucleus accumbens did not induce anxiety- and depression-like behaviors but lowered resilience to the social-stress induced depression by attenuating the paracellular barrier against blood-circulating interleukin-6 (21 kDa)." (PMID 36978081, 2023). "Conditional knockdown of CLDN5 in the nucleus accumbens did not induce depression behaviors but did induce depression following microdefeat at levels below the threshold to induce depression compared to mice without CLDN5 knockdown." (PMID 37937070, 2023). "Finally, CLDN5 and TBC1D1 were well-validated and identified as the hub crosslinks between ED and depression." (PMID 38111702, 2023). "Therefore, it is significant to explore the specific mechanisms of CLDN5 and TBC1D1 in the crosslink of ED and depression." (PMID 38111702, 2023). "In mice, viral-mediated downregulation of Cldn5 in the PFC is sufficient to promote anxiety- and depression-like behaviours including social avoidance, anhedonia, and helplessness supporting a causal role in the establishment of maladaptive stress responses and possibly, mood disorders." (PMID 35013188, 2022). "Animal studies and human postmortem studies have demonstrated that stress can cause blood–brain barrier (BBB) leakiness by reducing the expression of tight junction protein claudin-5, which promotes peripheral inflammatory cytokines to cross the BBB in depression." (PMID 35054436, 2021). "CLDN5 mRNA was increased in the occipital cortex (P = 0.0505) and cerebellum (*P = 0.0284) in bipolar brains, while OCLN was significantly increased in the occipital cortex (*P = 0.0397) of depression brains." (PMID 33139732, 2020). "Downregulation of claudin-5 protein coupled with stress-induced recruitment of peripheral immune signals resulted in increased BBB permeability and passage of blood proteins such as IL6 and the development of depression-like behaviours." (PMID 30691500, 2019). "Studies of postmortem brain tissue from patients with depression has found reduced expression of claudin-5, particularly in the nucleus accumbens and hippocampus, along with increased expression of FoxO1 and of histone deactylase 1 (HDAC1), both of which repress the CLDN5 gene." (PMID 39157756, 2024). "However, Bifidobacterium longum EPS significantly suppressed LPS-induced anxiety-/depression-like behaviors, hippocampal NF-κB+/Iba1+ cell population, and blood LPS level and induced LPS-suppressed hippocampal BDNF+/NeuN+ cell population and claudin-5 expression." (PMID 35672451, 2022).
schizophrenia (33 papers, 2017 to 2025). A major psychotic disorder characterized by abnormalities in the perception or expression of reality. "Studies have shown a significant association between the rs10314 variant and schizophrenia diagnosis in 22q11DS, with these individuals producing only about 25% of the normal CLDN5 levels, potentially leading to increased BBB permeability." (PMID 39940642, 2025). "Studies in Chinese and Iranian cohorts have also identified a slight genetic association between CLDN5 and the development of schizophrenia." (PMID 39940642, 2025). "A single nucleotide polymorphism rs10314 is located in the 3’-untranslated region of claudin-5 and has been shown to be a risk factor for schizophrenia." (PMID 38898501, 2024). "For schizophrenia, a variant in the claudin-5 gene is reported, leading to suppression of claudin-5." (PMID 38891789, 2024). "A SNP in the 3’-untranslated region of CLDN5 (rs10314) is very weakly associated with the prevalence rate of schizophrenia in many races." (PMID 36978081, 2023). "We have also previously reported on the discontinuity of claudin-5 immunoreactivity in the parietal lobe of schizophrenia patients which we further linked to the presence of the rs10314 variant in the CLDN5 gene." (PMID 33139732, 2020). "A single nucleotide polymorphism in claudin-5 is also associated with the development of schizophrenia." (PMID 31426497, 2019). "Several studies have pinpointed a single nucleotide polymorphism (SNP) in the 3′ untranslated region of the claudin-5 gene that is linked to schizophrenia." (PMID 30691500, 2019). "Taken together, the behavioural data presented here suggest a profound link between the gene-dosage effect of claudin-5 and manifestations of many schizophrenia-associated symptoms." (PMID 28993710, 2018). "Here, we show that a variant in the claudin-5 gene is weakly associated with schizophrenia in 22q11DS, leading to 75% less claudin-5 being expressed in endothelial cells." (PMID 28993710, 2018). "Various genes show associations with schizophrenia and a very weak nominal association with the tight junction protein, claudin-5, has previously been identified." (PMID 28993710, 2018). "Here, we describe the involvement of the most enriched TJ protein at the BBB, claudin-5, in predisposing an increased risk of schizophrenia in individuals with 22q11DS." (PMID 28993710, 2018). "A single nucleotide polymorphism located in the 3’-untranslated region of the CLDN5 locus is also related to schizophrenia." (PMID 29212157, 2017). "Here, we focus on the endothelial tight-junction protein claudin-5 (CLDN5), because the CLDN5 gene is mapped to the schizophrenia-associated 22q11.2 deletion region, and a single nucleotide polymorphism in the CLDN5 locus is also linked to schizophrenia." (PMID 29212157, 2017). "Suppression of CLDN5 is associated with psychosis-like symptoms; deficits in learning, memory and sensorimotor control in mice; symptoms similar to those found in schizophrenia." (PMID 40276385, 2025). "However, many studies have now shown that rs10314 is a very weak risk factor of schizophrenia, indicating that rs10314 can lower the “threshold” to induce psychiatric diseases by reducing tight junction ‘free’ CLDN-5 in an additive manner." (PMID 38898501, 2024). "Furthermore, rs10314, a single nucleotide polymorphism (SNP) in CLDN5, is known as a weak risk factor of schizophrenia." (PMID 38898501, 2024). "Taken together, these results suggest that BBB dysfunction caused by a deficiency of CLDN5 may lead to a high incidence of schizophrenia in 22qDS." (PMID 36676170, 2023). "Claudin 5 is implicated as a singular driver in multiple disease states including some neuroinflammation states and plays major roles in disease states from carcinomas to schizophrenia and other endothelial barrier dysfunctions." (PMID 35789221, 2022).
schizophrenia (continued). "Since 5-HT1A functions as a target for schizophrenia, further studies are required to determine whether 5-HT1A-targeting drugs improve the localized PKA activation and endothelial CLDN5 loss in schizophrenia in future experiments." (PMID 33383868, 2020). "Similarly, loss of claudin-5 is associated with reduced acoustic pre-pulse inhibition, a schizophrenia-related behavioural abnormality." (PMID 33139732, 2020). "The minor allele of the rs10314 CLDN5 variant may increase risk for schizophrenia." (PMID 41358302, 2025). "Furthermore, loss of claudin-5 in the nucleus accumbens is associated with depressive phenotypes while loss of claudin-5 in the hippocampus and medial prefrontal cortex is associated with schizophrenia-related behaviours in rodents." (PMID 33139732, 2020). "The loss of claudin-5 expression and the corresponding increase in BBB permeability also regulates schizophrenia-like behaviors in mice, such as impairments in cognitive function and sensorimotor gating." (PMID 39367201, 2025). "Another study induced patient-derived stem cells to differentiate into BBB cells and found impaired BBB integrity in 22q11DS + schizophrenia patients, with markedly dysfunctional CLDN5 expression observed." (PMID 39940642, 2025). "The expression of CLDN5, as measured by immunohistochemistry and quantitative PCR, is decreased in patients with schizophrenia and depression according to postmortem analysis." (PMID 40276385, 2025). "Compared to controls, schizophrenia patients exhibited significantly higher mean serum zonulin levels and reduced serum CLDN5 levels." (PMID 39940642, 2025). "In postmortem hippocampal tissues of schizophrenia patients, abnormally elevated CLDN-5 mRNA levels were observed in some individuals, yet the corresponding CLDN-5 protein expression was substantially reduced." (PMID 39940642, 2025). "The suppression of specific proteins, such as claudin-5, has been linked to learning deficits and anxious behaviors, underscoring the connection between the BBB and schizophrenia." (PMID 38673018, 2024). "Of note, 15–25% of patients with 22q11DS have experienced psychiatric disorders, mainly schizophrenia, but almost half of the patients with 22q11DS with rs10314 (CLDN-5 expression level is further declined) have experienced schizophrenia." (PMID 36978081, 2023). "PDE4B and PDE4D inhibitors, which upregulate CLDN-5 level by cAMP-mediated pathway, are considered as potential drugs for schizophrenia and dementia." (PMID 36978081, 2023). "For example, the mRNA level of Claudin-5 was increased in the prefrontal cortex of schizophrenia patients, while the protein expression was decreased." (PMID 36051441, 2022). "Claudin-5 levels negatively correlated with the age of onset of schizophrenia in the orbitofrontal grey matter (r = −0.5510, *P = 0.0333)." (PMID 33139732, 2020). "We previously found that the brain region-selective breakdown of the CLDN5 protein appears in patients with schizophrenia." (PMID 33383868, 2020). "Taken collectively, these results highlight the pathobiological relevance of the region-selective CLDN5 breakdown in schizophrenia." (PMID 33383868, 2020). "In post-mortem specimens from individuals with schizophrenia, claudin-5 protein levels were decreased in the frontal cortex and this reduction was associated with PKA signalling." (PMID 30691500, 2019). "Here, we were able to identify an aberrant pattern of claudin-5 immunoreactivity in 62% of schizophrenia patient brains based on an analysis of claudin-5 levels." (PMID 28993710, 2018). "Our data obtained from inducible ‘knockdown’ mice now suggests a link between the gene-dosage effect of claudin-5 and the onset of schizophrenia-like characteristics in this mouse model." (PMID 28993710, 2018).